IFNG (interferon gamma)
Diseases named in the same sentence as IFNG in open-access papers (continued):
Sharing a sentence is not in itself a finding about the gene and the disease.
tumor (continued). "Supernatant IFNγ was measured and revealed that HSC-derived cells that were isolated from the tumor demonstrated specific presentation of tumor-derived antigens to activated T cells." (PMID 30333482, 2018). "The combination also promoted IFNg, IL12 and granzyme B production in the tumor microenvironment and decreased the formation of liver metastasis in a very early phase of tumor development, enabling 90% survival." (PMID 30356111, 2018). "Radiation also induces the secretion of IFNγ and CXCL-10 in a melanoma mouse model, effecting the infiltration of CTLs, correlating with the inhibition of tumor growth and improved survival in mice." (PMID 30487462, 2018). "IFNγ and IL-2 cytokine production was observed only when TAG72-BBζ CAR T cells were co-cultured with antigen-positive tumor targets, OVCAR3, LS174T, and OV90." (PMID 30510550, 2018). "For example, murine liver NK cells contribute to natural antimetastatic function against TRAIL sensitive tumor cells and constitutive TRAIL expression on these NK cells is IFNγ dependent." (PMID 28408907, 2017). "The M1 phenotype can be induced by interferon gamma (IFN-γ) and lipopolysaccharides and have been shown to have cytotoxic effects on tumour cells." (PMID 28148268, 2017). "In the Checkmate 275 study with nivolumab in mUC, a 25-gene interferon-gamma (IFN-γ) signature derived from crude extract (EdgeSeq, HTG Molecular Diagnostics Tucson, AZ, USA) was used to assess 177 tumor samples from pretreatment biopsies." (PMID 29157296, 2017). "Proinflammatory cytokines (IFNγ, MCP1, MIP1α, and TNFα) and myeloid differentiation factor (Endoglin) were increased in myeloid cells from p65 KO tumor, which demonstrated an influence on CD8+T cell proliferation." (PMID 29062041, 2017). "IFNγ secretion by CD8+ T cells is critical for therapy efficacy having anti-proliferative and pro-apoptotic effects on tumour cells." (PMID 28561041, 2017). "These experiments provide initial evidence that IDC cells, in part via IFNγ, induce endogenous IDO1 expression by ECs serves as an evasive mechanism against TSP1 of tumour dormancy." (PMID 29156701, 2017). "Th1 Lymphocytes produce Interferon Gamma (IFN-γ), Tumor Necrosis Factor Alpha (TNF-α), and Interleukin-2 (IL-2), which are all essential for tumor rejection." (PMID 28473858, 2017). "For example, interferon gamma (IFN-γ)-expressing Th1 CD4+ T cells contribute to antitumor immunity by blocking neoangiogenesis and promoting recruitment of tumor-killing cells including CD8+ T and NK cells." (PMID 28848560, 2017). "We observed that IFNγ and granzyme-B expression on Vβ8.1/2+CD8+T cells in the spleens of tumor-bearing mice injected with IL-12 and IL-15 neutralization antibodies was significantly reduced compared with the expression in unneutralized tumor-bearing mice." (PMID 28052005, 2017). "We found that both tumor-derived Lin-EpCAM-CD73+CD90+ cells and their matched normal counterparts upregulate PD-L1 following exposure to TNFα and IFNγ, as shown in histograms overlays." (PMID 28878242, 2017). "Galectin antagonists increase intratumoral IFNγ diffusion, CXCL9 gradient and tumor recruitment of adoptively transferred human CD8+ T cells specific for a tumor antigen." (PMID 28986561, 2017). "In the current study, we show that DC matured in the presence of a combination of IFNγ and ligands for TLR3 (poly I:C), TLR4 (LPS), and TLR8 (R848) display features crucial for triggering efficient T cell-mediated anti-tumor responses." (PMID 28601925, 2017). "Galectin antagonists increased strongly CXCL9 expression in tumor xenografts and human biopsies, supporting the notion that galectin-3 lattices in the tumor ECM are the important players of IFNγ retention." (PMID 28986561, 2017). "Once tumours were palpable, a combination of live or irradiated MHC-positive DFT1 cells and IFNγ was injected into the tumours." (PMID 28695294, 2017).
tumor (continued). "Besides tumor cells, large populations of Tregs, TAMs, and possibly other host cells provide high levels of immunosuppressive mediators, thereby strongly limiting the fraction of cells competent to produce the crucial pro-inflammatory cytokines, such as IFNγ and IL-12." (PMID 28275576, 2017). "In the murine cancer model, targeting of IL-17A inhibited PDL1 expression in the tumor microenvironment, decreased the percentage of Treg cells in tumor-infiltrating lymphocytes, and promoted CD4+ and CD8+ T cells to secrete interferon gamma." (PMID 27935862, 2017). "All MT/Shc2F/2F tumours displayed an IFNγ-inducible increase in nuclear STAT1 levels relative to MT/ShcA+/+ and MT/Shc313F/313F tumours, which are immunosuppressive." (PMID 28276425, 2017). "CD4+CD25hiFoxP3+ T cell depletion resulted in increased proliferation and tumor-specific IFNγ secretion of the T cells, indicating that the CD4+CD25hiFoxP3+ T cells were capable of suppressing the expansion of tumor-reactive T cells." (PMID 28401257, 2017). "Overall, these results indicate that the combination of h11c-DC, IFNγ and COX2-I effectively induces strong responses to overcome tumor growth." (PMID 29190690, 2017). "After treatment with anti-CD4 the number of IFNγ+CD8+ T cells in the DLN of mice with control EMT6 tumors was increased ~3-fold relative to PBS treated mice, in keeping with the decreased tumor growth." (PMID 28234914, 2017). "The adaptive pattern of PD-L1 expression in the tumor microenvironment can be further accentuated by amplification of the 9p24.1 locus, which contains PD-L1, −L2 and JAK2, the latter of which is an interferon-gamma-responsive element." (PMID 28344809, 2017). "Due to exhaustion of CD8+ T cells, tumor cells become very aggressive and secrete several pro-inflammatory cytokines, such as tumor necrosis factor alpha (TNF-α), interleukin-2 (IL-2), and interferon gamma (IFN-γ)." (PMID 28878676, 2017). "Trapping IFNγ in the ECM would reduce the CXCL9/10 gradient, thereby limiting T-cell infiltration in the tumor." (PMID 28986561, 2017). "Our data indicate that the tumor ECM has an essential role in the retention of IFNγ by galectin-3, as collagenase D treatment resulted in increased IFNγ availability and CXCL9 gradient formation." (PMID 28986561, 2017). "We investigated the correlation of the IFNγ response signature with JAK1 expression since expression is reduced in cell lines and tumor samples with a JAK1 frameshift." (PMID 29121062, 2017). "A large majority of tumour infiltrating CD8+ PD-1+ T cells (63.3%) are primed to produce IFNγ with the potential to deliver a lytic activity in situ." (PMID 28128200, 2017). "Nevertheless, this data clearly support the concept that combining MEKi with immunotherapy enhances IFNγ production, which has the potential to significantly enhance MHC-I expression and, consequently, tumor cell immunogenicity." (PMID 28928458, 2017). "GM-CT-01 was also studied as a booster of tumor-infiltrating lymphocyte (TIL) function; this action is due to an increase in the release of IFNγ, allowing tumor regression." (PMID 29258258, 2017). "TCP-1/TNFα combined with TCP-1/IFNγ induced massive cell death in the tumor (>90 %) as shown by the TUNEL staining and also cell death of the tumor vasculature." (PMID 27342639, 2016). "This anti-tumor impact was primarily iNOS-mediated as indicated by the inhibitory effect that L-NMMA had on Gr1dim cells, blocking their CpG+IFNγ-induced tumoricidal properties (6 vs 7 ***p < 0.0001)." (PMID 27341020, 2016). "Using B16-F10 tumor-bearing WT and hAAT+/+ mice, we performed IRP of tumor-bearing extremities and determined changes in VEGF, IL-12p40, IFNγ, and IL-10 transcription levels in the immediate inoculation site." (PMID 28003813, 2016). "In murine tumor models, the blockade of PD-1/PDL1 interaction led to enhanced interferon gamma (IFNγ) secretion and anti-metastatic activity of iNKT cells." (PMID 27631416, 2016).
tumor (continued). "IFNγ-activated STAT1 signaling induces apoptosis, halts progression through cell cycle and boosts anti-tumor immunity." (PMID 26988232, 2016). "Since TAA+cytokine-activated DCs induced highest IFNγ upon interaction with host splenocytes, in later experiments DCs (1 × 106/scaffold) activated with TAA+cytokine were used for the tumor treatment." (PMID 27223090, 2016). "iNKT cell-derived cytokines, such as IFNγ and IL-2, are reported to activate cytotoxic T lymphocytes (CTL) and NK cells, which effectively abrogate the actions of tumor cells." (PMID 27631416, 2016). "The local accumulation of NK cells can also facilitate the development of anti-tumor CD8+ cytotoxic T lymphocyte responses and increase the number of tumor-specific IFNγ-producing cells." (PMID 27145284, 2016). "To further clarify how the cells in the tumor died after TCP-1/TNFα and TCP-1/IFNγ combined treatment, we used the colon 26 cells to determine the effect of TNFα combined with IFNγ in vitro." (PMID 27342639, 2016). "In contrast, the V3 model assumes that, upon entering the tumor microenvironment, a subset of CD8+ T cells lose cytotoxic activity and an ability to produce IFNG, that is they become deactivated." (PMID 28101055, 2016). "Subsequently, macrophage IL-12 amplifies the miR-18a-mediated anti-tumor activity by activation of liver NK and NKT cells in an IFNγ dependent manner." (PMID 27028860, 2016). "In addition, trying to capture the IFNG response suggested specific experimental conditions where additional experiments could help refine our understanding of the dynamic response of CD8+ T cells to tumor localization." (PMID 28101055, 2016). "In contrast, the increase in fold difference in median IFNγ and VEGF expression levels suggested that these cytokines were mostly generated by cells of human origin that is, PMP tumor cells." (PMID 26833741, 2016). "This is noteworthy in the tumour setting, as effector memory CD8+ T cells have been shown to exhibit inferior anti-tumour immunity to central memory CD8+ T cells, despite being efficient IFNγ producers." (PMID 27599546, 2016). "Compared with the unconjugated TNFα and IFNγ, the conjugated groups through TCP-1 further increased the infiltration of both CD8+ and CD4+ T cell in the tumor." (PMID 27342639, 2016). "While circulating tumor-specific T cells exhibited normal effector function, TILs isolated from the tumor-draining lymph node (TDLN) showed a markedly exhausted phenotype, characterized by decreased IFNγ expression and upregulation of CTLA-4 and Lag-3." (PMID 27314056, 2016). "We found that TNFα (1 μg/mouse) or IFNγ (5 μg/mouse) slightly increased tumor apoptosis while conjugation with TCP-1 peptide significantly inhibited tumor growth and increased tumor cell apoptosis." (PMID 27342639, 2016). "Membrane bound CD40 ligand triggered tumor cell apoptosis via activation of JNK/activation protein-1 and stimulated the secretion of both tumor necrosis factor alpha and interferon gamma, which ultimately activated the caspase 3/7 pathway." (PMID 27494901, 2016). "Such in vivo immune modulation by curcumin led to enhanced IFNγ+ CD4 and CD8 T cells with heightened capacity to lyse syngeneic 4T1 tumor cells, resulting in inhibition of tumor growth." (PMID 27405665, 2016). "Although MHCI and PD-L1 were both enhanced by interferon gamma (IFN-γ), they have competing roles as MHCI promotes antigen-specific effector responses, while PD-L1 renders tumour cells resistant to T-cell effector functions." (PMID 28008921, 2016). "These tumor-specific CTL had characteristics similar to antiviral CTL, including strong expression of activation markers and co-expression of IFNγ and TNFα." (PMID 26961085, 2016). "When we analyzed tumor-infiltrating CD8+ T cells, we found that majority of the population produced IFNγ (~80%) and Granzyme B (~70%) in the tumor stroma of WT mice." (PMID 25760243, 2015).
tumor (continued). "IFN-γ (IFNG) is a pro-inflammatory cytokine that modulates many immune-related genes and shapes the tumor microenvironment in such a way that it shows both anti- and pro-tumorigenic activities." (PMID 26556872, 2015). "Here, the key predictive factor is most likely the presence of tumor-infiltrating lymphocytes (TILs) inside the tumor, and IDO1 is secondarily induced in response to IFNγ produced by those TILs." (PMID 25691885, 2015). "Both in vivo and in vitro studies confirmed that a low-dose of curcumin induced effective anti-tumor response by increasing CD8+ cytotoxic T cells and IFNγ secretion; whereas a higher-dose of curcumin was detrimental for T cells." (PMID 26464579, 2015). "Notably, there were about 15% of tumor-infiltrating CD4+ T cells expressing IFNγ in WT mice whereas there were only 9% of them in KO mice, suggesting that AMPK deficiency may impair IFNγ production in tumors." (PMID 25760243, 2015). "In summary, effector function of CAR+ T cells, as manifested by IFNγ expression, was restricted to ROR1+ tumor cells and ROR1RCD28+ T cells produced more IFNγ than did ROR1RCD137+ T cells in response to ROR1." (PMID 26030772, 2015). "As MHC II cell surface expression can be induced in nucleated cells by the cytokine, interferon gamma (IFN-γ), through the JAK/STAT signaling cascade, the molecular mechanisms regulating the MHC II status of tumor cells is of clear importance." (PMID 25690042, 2015). "A significant reduction in 5TGM1-GFP+ cells in the BM, accompanied by an upregulation in IFNγ-secreting CD8+ T cells was observed, along with a diminished tumor load in the spleen and reduced serum M-spike." (PMID 25871384, 2015). "CXCL3 was still firmly expressed by tumor cells in both Calu-6 and SK-MES tumors from myeloablated and hrIL-27-treated mice, while a faint IFNγ production was only detected in the latter." (PMID 25638163, 2015). "5AZA2-treated tumor cells induced a higher yield of tumor-infiltrating CD4, CD8 T cells, and NK cells and IFNγ production was also elevated in both T-cell compartments." (PMID 25699047, 2015). "Our model predictions of adenovirus concentration, tumor size, concentrations of CD8 + T effectors in blood and tumor, gene expression of IFNG and TNF α matched the experimental data." (PMID 26048402, 2015). "It seems that during tumor development, inflammatory environment (IL1β and IL23) modulate the cytokine profile of γδT cells from primary IFNγ toward proinflammatory IL17, which support tumor progression." (PMID 25699053, 2015). "The concentrations of the following cytokines including IL-23, IL-25, IFNγ, CD40L and TNFα in WF collected from patients with T2 tumor tended to be higher than those with T1 tumor." (PMID 26313265, 2015). "Through upstream regulator analysis it was predicted that several interferons, IFNγ, IFNα, IRF3, IRF7, and IFNA2, were up-regulated for spleens from old tumor bearing mice." (PMID 26497558, 2015). "In the model of adaptive immune resistance IFNγ-driven expression of PD1 ligands CD274 and PDCD1LG2 on tumour cells and the microenvironment limits local T-cell responses." (PMID 26362649, 2015). "52,53 This process requires direct contact between the pre-mNK and a tumor cell or infected fibroblast, and subsequent upregulation of MHCII as well as IFNγ and PD-L1." (PMID 26405570, 2015). "Our study showed that ARTD9 can inhibit the IFNγ/STAT1-dependent anti-proliferative and pro-apoptotic activities of tumor suppressor IRF1 while simultaneously activating the STAT1/IRF2-mediated anti-apoptotic-pro-survival pathways in HR-subtype DLBCL cells." (PMID 26654227, 2015). "In contrast to HPV-negative tumor tissues, HPV-positive tumor samples showed significantly higher numbers of infiltrating IFNγ+ CD8+ T lymphocytes, IL-17+ CD8+ T lymphocytes, myeloid dendritic cells and proinflammatory chemokines." (PMID 25949860, 2015).
tumor (continued). "First pre-clinical studies of the combination of these antibodies to achieve blockade of both CTLA-4 and PD-1 showed increased tumor infiltration by CD4+ and CD8+ T-cells, enhanced IFNγ and TNFα production, and reduced amounts of Tregs." (PMID 24822170, 2014). "Cells isolated from the tumor of mice treated with either CpG ODN or 3M-052 had higher levels of expression of IL-12, IFNγ and granzyme B than tumor infiltrating cells from untreated mice (p <.05)." (PMID 24982761, 2014). "Tumor regressions in vivo due to anti-HER2 mAb therapy also require an effective adaptive anti-tumor immune response to reach optimal therapeutic effects, and levels of CD8 and interferon-gamma have been shown to correlate with anti-HER2 treatment." (PMID 25774617, 2014). "It should also be stated that other (immuno)modulators, namely IFNγ and HDAC inhibitors, were recently reported to cooperate with H-1PV for tumor suppression in human carcinoma animal models." (PMID 24822170, 2014). "Again, peripheral blood mononuclear cells (PBMC) from EC bearing PBS and NLGP treated mice were co-cultured with tumor (EC) cells and culture supernatant was analyzed for VEGF and IFNγ content." (PMID 25391149, 2014). "In the virus-infected tumor cells, MHC I and immunoproteasome subunits are upregulated by IFNγ, resulting in the increased TAA (OVA) presentation to CD8+ T cells (B3Z cells)." (PMID 24827739, 2014). "Already 15 years ago CD4+ Th cells of the Th1 (predominantly IFNγ) and Th2 (predominantly IL-4) cells as well as CD8+ T cells have been shown to play a key role for an effective anti-tumor response." (PMID 24885059, 2014). "Our findings demonstrate that the addition of GK-1 to BMDCs loaded with MAGE-AX decreases the rate of tumor growth and increases the survival of mice and the expression of CD86 and IL-12 in the BMDCs, as well as the levels of CD8 IFNγ producing T cells." (PMID 25759825, 2014). "Interferon-gamma and IL-12 promote development of T-helper-1 (TH1) immune responses, which play a key role in producing anti-tumor immune responses." (PMID 24069344, 2013). "As it has been observed for tumor cell lines, LIGHT-induced death of motoneurons is also tightly regulated by the proinflammatory cytokine IFNγ." (PMID 26316997, 2013). "In particular, CTLA-4/B7 blocking in murine models results in increased IL-2 and interferon-gamma (IFN-γ) production by lymphocytes, increased expression of major histocompatibility complex (MHC) class I molecules, and markedly increased tumor killing." (PMID 23634660, 2013). "Interferon-gamma (IFN-gamma) and interleukin-6 (IL-6) are multifunctional cytokines that regulate immune responses, cell proliferation, and tumour development and progression, which frequently have functionally opposing roles." (PMID 23384097, 2013). "In contrast, 25 % of iNKT cells from MC-38-CEA tumor-bearing mice treated with αGC/sCD1d-anti-CEA fusion protein still produced IFNγ, while only 9 % iNKT cells were IFNγ+ in mice treated with the irrelevant αGC/sCD1d-anti-HER2 fusion protein." (PMID 23242316, 2013). "The execution of tumor rejection requires production of interferon (IFN) γ by CTLs as demonstrated by neutralizing mAbs and with T cells derived from IFNγ-/- mice." (PMID 24764534, 2013). "These T cells effectively lysed a variety of CD20+ tumor cells at low E:T ratios and secreted abundant IFNγ, TNF-α, and IL-2 upon tumor recognition, highlighting their CD20 specificity and potent effector function." (PMID 24358223, 2013). "In line with this, vaccination with staphyloccocus enterotoxin A expressing tumor-exosomes significantly inhibited tumor growth and prolonged the survival time by increasing IL2 and IFNγ secretion and by promoting T helper (Th), CTL and NK activation." (PMID 23190502, 2012).